TCF12 (transcription factor 12)
Diseases named in the same sentence as TCF12 in open-access papers (continued):
Sharing a sentence is not in itself a finding about the gene and the disease.
liver cancer (continued). "This study aims to explore how the interaction between TCF12 and hypoxia-inducible factor 1-alpha (HIF-1α) affects vascularization and drug sensitivity in liver cancer." (PMID 40190273, 2025). "Immunohistochemical staining was then performed on liver cancer tissue microarrays to investigate the correlation between TCF12 and CD31, as well as to evaluate the impact of TCF12 expression on the prognosis of liver cancer patients." (PMID 40190273, 2025). "To investigate the effects of TCF12 and HIF-1α on tube formation and drug sensitivity in liver cancer vascular ECs, we examined three groups: a control group, a TCF12 shRNA group, and a TCF12 shRNA plus HIF-1α group." (PMID 40190273, 2025). "The analysis revealed a positive correlation between TCF12 and CD31 expression in liver cancer tissues." (PMID 40190273, 2025). "Furthermore, several experiments—including scratch assays, tube formation assays, cell permeability assays, and cell viability assessments—were conducted to explore the effects of TCF12 and HIF-1α on vascularization and drug sensitivity in liver cancer." (PMID 40190273, 2025). "Additionally, we performed cell-based functional assays to examine the effects of TCF12 and HIF-1α on migration, tube formation, permeability, and other phenotypic characteristics of liver cancer ECs." (PMID 40190273, 2025). "Initially, Western blot analysis was performed to compare TCF12 expression levels in liver cancer tissues vs adjacent non-cancerous tissues." (PMID 40190273, 2025).
lung carcinoma (1 paper, 2012). "However, a DNA inversion close to the TCF12 gene was recently found in lung cancer patients indicating that this protein may be playing a role in regulating gene response in the lung." (PMID 22897824, 2012).
Myeloma (1 paper, 2024). "Additionally, the most activated TFs in each subgroup within the M1-M5 modules were identified as follows: MAF in the C0 IGLL5+ Myeloma Cells subgroup, LEF1 in the C1 IGHG4+ Myeloma Cells subgroup, TCF12 in the C2 MALAT1+ Myeloma Cells subgroup, and CREB5 in the C3 IGHG1+ Myeloma Cells subgroup." (PMID 39281682, 2024).
thyroid (1 paper, 2016). "TCF12, KDM5C, IGF2BP3 and MAP4K3 mutations newly identified in our study might possibly be follicular tumor-specific thyroid mutations." (PMID 27626165, 2016).
tumor (41 papers, 2009 to 2025). "Amplifications of CDK4/6, CCND2, PDGFRA, MYCN as well as RB1 mutation/homozygous deletion, MET alterations, PIK3R1/PIK3CA mutations, NOTCH1 mutations and TCF12 mutations are also associated with tumor progression & shorter survival in IDH mutant astrocytomas." (PMID 40949165, 2025). "Among the 75 germline non-ref NUMTs, the one on the intronic region of TCF12 (chrM:7179–7295-to-chr15:57220850, present in one individual) would be interesting as TCF12 is a known tumor-associated gene (COSMIC databases,)." (PMID 38566210, 2024). "We next sought to determine the effects of TCF12 loss on the proliferation of GL261 tumor stem cells." (PMID 37046694, 2023). "Our study shows that TCF12 deficiency severely impairs proliferation of tumor cells in vitro by disrupting/blocking the G1 to S phase transition." (PMID 37046694, 2023). "We find that TCF12 deficiency impairs the proliferation of tumor cells in vitro and slows tumor growth in vivo resulting in improved overall survival." (PMID 37046694, 2023). "To gain insight into the effects of TCF12 loss on tumor growth and progression in vivo, and overall survival, we performed intracranial injection of TCF12-competent and TCF12-deficient GL261 cells in mice." (PMID 37046694, 2023). "Further validation of Arhgap42 and Tcf12, the functions of which in cancer were previously unclear, indicated that both serve as tumor suppressor genes for Brca1-associated tumorigenesis." (PMID 37063417, 2023). "Using the murine GBM model, GL261, and human GBM cells, we demonstrate that TCF12 loss severely impairs the proliferation of tumor cells in vitro." (PMID 37046694, 2023). "A somatic TCF12 p.L352* nonsense mutation present in all F12 tumor foci at heterozygous VAF suggested early co-occurrence with the H3F3A p.K27M mutation, as well as selective advantage." (PMID 32680567, 2020). "We profiled gene expression in 8 TCF12-mutated and 45 wild-type tumours within 1p/19q co-deleted samples." (PMID 26068201, 2015). "All TCF12 wild-type tumours showed nuclear expression in a heterogeneous cell population, whereas several TCF12-mutated tumours showed nuclear and cytoplasmic staining." (PMID 26068201, 2015). "We show that these mutations compromise TCF12 transcriptional activity and are associated with a more aggressive tumour type." (PMID 26068201, 2015). "To identify additional TCF12-mutated AO tumours, we conducted targeted sequencing of a further 83 AO." (PMID 26068201, 2015). "We profiled the extent of necrosis, microvascular proliferation and the mitotic index available for TCF12 wild-type or mutated tumours." (PMID 26068201, 2015). "On the basis of our combined sample of 134 tumours, the mutation frequency of TCF12 in AO is 7.5% (95% confidence interval 3.6–13.2%)." (PMID 26068201, 2015). "The observation that the frequency of TCF12 mutations is higher in AO as compared with grade II tumours (P=0.049, χ2-test) is compatible with TCF12 participating in the generation of a more aggressive phenotype." (PMID 26068201, 2015). "In summary, the experiments confirmed that the tumor associated alternative TSS usages observed for TCF12, OSBPL1A and TRAK1 were indeed due to altered expression in the carcinoma cells, and not a consequence of altered tissue composition." (PMID 21999571, 2011). "However, among tumor-free patients, Asian patients, and those with low plasma protein levels, high TCF12 expression was associated with significantly shorter OS compared to low expression." (PMID 40190273, 2025). "Another associated gene, TCF12, facilitates cell development and differentiation and probably controls the activation of cancer-associated fibroblasts, which are critical markers of tumor progression." (PMID 37520246, 2023).
tumor (continued). "Additionally, TCF12 expression has also been found to be associated with advanced tumor stages and poor prognosis in breast and lung cancers." (PMID 37760480, 2023). "Two of these 43 tumours harboured frameshift mutations in TCF12 (E548R and D171fs)." (PMID 26068201, 2015). "As with our series, these TCF12 mutations were exclusive to IDH-1p/19q co-deleted tumours." (PMID 26068201, 2015). "Five tumours harboured TCF12 mutations—G48fs*38, M260fs*5, R326S, D455fs*59 and delN606." (PMID 26068201, 2015). "Finally, we found that the loss of TCF12 transcriptional activity was associated with a more aggressive tumour phenotype." (PMID 26068201, 2015). "Notably, aberrant TCF12 expression is closely linked to tumor progression." (PMID 40190273, 2025). "Since HEB/TCF12 is not deleted nor inactivated by deleterious mutations in human T-ALL, we addressed the possibility that down-regulation or genetic inactivation of HEB targets with tumor suppressor function could also be a mechanism associated to and/or selected for during disease progression." (PMID 35401501, 2022). "Interestingly, it has been reported that TCF12 may have a haploinsufficient tumor suppressor role which increases the risk of developing AO in those patients harboring a TCF12 germline mutation." (PMID 34675774, 2021). "The PPI analysis shows TCF12 is involved in the regulation of cell differentiation and transcriptional misregulation, highlighting the potential role of cg21831937 in inhibiting tumour progression by regulating TCF12 expression." (PMID 41292185, 2025). "Other co-existing genetic alterations associated with tumor progression and shorter survival in oligodendroglioma include homozygous PIK3CA mutation, TCF12 mutation and increased MYC signaling." (PMID 40949165, 2025). "SW480, a cell line established from a primary CRC tumor, exhibits low TCF12 expression, whereas SW620, a paired cell line established from lymph node metastasis of the same patient, expresses high levels of TCF12." (PMID 39768127, 2024). "In the TCGA-COAD (GA) dataset, there were 33 patients whose tumor tissues simultaneously expressed higher levels of TCF12 mRNA, MALAT1, and β-catenin mRNA." (PMID 39768127, 2024). "These MRIs showed significant interval growth of tumors in mice injected with control and scramble tumor cells; however, mice that received TCF12 KO cells showed much less growth during that interval." (PMID 37046694, 2023). "Using mouse models of human IDH-GBM, we describe a role for TCF12 in the regulation of GSCs, tumor progression, and overall survival." (PMID 37046694, 2023). "Histologic analysis of the tumors showed unusual tumor histology, noting the prominent mucinous extracellular matrix in TCF12 KO tumors." (PMID 37046694, 2023). "Nevertheless, our in vivo and in vitro data coupled with the transcriptomic data clearly demonstrate a role for TCF12 in the regulation of proliferation of tumor cells." (PMID 37046694, 2023). "Overexpression of TCF12, on the other hand, leads to an increase in the proliferation of tumor cells in vitro and more aggressive tumor progression in vivo." (PMID 37046694, 2023). "We found that some key regulators of the cell cycle and markers of mitosis were significantly downregulated in the TCF12 KO tumor cells." (PMID 37046694, 2023). "It will particularly be interesting to look at the role of collagen fibers in the TCF12 KO tumors in delaying tumor growth." (PMID 37046694, 2023). "Using the CRISPR/Cas9 system, we deleted TCF12 in GL261 tumor cells and selected out single knockout (KO) clones." (PMID 37046694, 2023). "There was also overall better survival in the TCF12 KO tumor-bearing mice compared to mice injected with control and scramble cells." (PMID 37046694, 2023). "We also find that TCF12 regulates the expression of some key regulators of the cell cycle in tumor cells." (PMID 37046694, 2023).
tumor (continued). "We then confirmed the presence of GSCs in this model by the neurosphere assay by culturing the scramble and TCF12 KO tumor cells in NSC medium and in a hypoxic environment." (PMID 37046694, 2023). "In this study, we reveal a new role for TCF12 in the regulation of the proliferation of GBM tumor cells from in vitro and in vivo data." (PMID 37046694, 2023). "Three weeks after intracranial injection of tumor cells, mice recipient of control and scramble cells developed significantly larger tumors than mice that were injected with TCF12 KO cells." (PMID 37046694, 2023). "We repeated the MRIs two weeks after the initial MRIs and we observed larger tumors in the mice that were injected with TCF12-overexpressing tumor cells compared to controls." (PMID 37046694, 2023). "Recent studies have highlighted the contributions of TCF12 to the progression of different tumor types, including colorectal, pancreatic, liver, and ovarian cancers." (PMID 37760480, 2023). "TCF12 KO tumors grew much slower and the mice bearing them lived much longer than control and scramble tumor-bearing mice." (PMID 37046694, 2023). "We observed a significant decrease of TCF12 KO tumor cells in the S phase of the cell cycle compared to control or scramble tumor cells." (PMID 37046694, 2023). "Phospho-histone 3 (pHH3) is a known marker of mitosis, and we observed downregulation of pHH3 in TCF12 KO compared to control and scramble tumor cells." (PMID 37046694, 2023). "In summary, our results indicate a tumor suppressor function of HEB/TCF12 in T-ALL to mitigate cell proliferation controlled by NOTCH1 in pre-leukemic stem cells and prevent NOTCH1-driven progression to T-ALL." (PMID 35401501, 2022). "Highlighting an almost complete impairment in neuronal migration both at 2 and 4 days after knockdown, our data extend to physiological development the reported role of Tcf12 in the migration of tumour cells." (PMID 35147187, 2022). "While E2A/TCF3 is annotated as a tumor suppressor gene (TSGene 2.0) with direct experimental and clinical evidence, HEB/TCF12 tumor suppressor function has been overlooked, despite the critical role of HEB in the T lineage." (PMID 35401501, 2022). "One analysis looking at the downstream effect of TCF12 alterations showed a downregulation of TCF21, EZH2, and BMI1 pathway and especially CDH1 (E-cadherin), which has been shown to be implicated in tumor characteristics and metastasis." (PMID 34675774, 2021). "Surprisingly, TCF12 was confirmed to activate the PI3K/AKT signaling pathway to affect tumor progression." (PMID 33413401, 2021). "TCF12, which is known to be involved in the regulation of cell growth and differentiation, has been reported to function as an oncogene or a tumor suppressor gene in the progression of various malignant tumors." (PMID 31534521, 2019). "Previous documents suggested a close correlation between TCF12 expression and tumor metastasis 14-17." (PMID 31534521, 2019). "Recently, TCF12 has been show to function as an oncogene or a tumor suppressor gene in tumor progression." (PMID 31534521, 2019). "Conversely, tumor growth was obviously decreased in mice injected with Huh7 cells with stable TCF12 knockdown (Huh7-shTCF12-2) compared to that of mice in the negative control (NC) group." (PMID 31534521, 2019). "Given the critical role of CXCR4 in HCC progression 20, 22, 25, 29 and the most obvious expression-altering gene in TCF12 knockdown cells, we decided to investigate the role and the underlying mechanism of CXCR4 in pro-tumor function of TCF12 in HCC." (PMID 31534521, 2019). "Clinically, elevated TCF12 expression was detected in the tumor tissues of CRC patients with a significantly higher rate of metastasis." (PMID 29435158, 2018). "Extracellular HSP90α (eHSP90α) can be a naturally occurring inducer of TCF12 overexpression in tumor." (PMID 29435158, 2018).
tumor (continued). "Mutations leading to truncation of a basic helix-loop-helix (bHLH) domain of the transcription factor TCF12 were previously detected in an aggressive type of 1p/19q-codeleted tumor." (PMID 28270234, 2017). "In conclusion, in the present study, we demonstrated that HDAC1 and TCF-12 expression were high in tumor samples from patients with in HCC." (PMID 27092878, 2016). "What is more, TCF12 has been found to suppress the expression of E-cadherin, which can lead to the metastasis of tumor cells." (PMID 27716259, 2016). "qRT-PCR confirmed de novo expression of the short TCF12 isoform (exon 1B) in many tumor samples and showed strong correlation to the exon array data (RS = 0.82, Spearman correlation)." (PMID 21999571, 2011). "Increased expression of TCF12 exon 1B in tumor samples was seen in 21 of 23 sample pairs (p = 0.001)." (PMID 21999571, 2011). "We observed only very few stained cells in the cancer stroma, corresponding to the weak expression of the short TCF12 mRNA isoform detected in LCM tumor stroma samples." (PMID 21999571, 2011). "Targeting genes such as LITAF, OSMR, and TCF12 could selectively disrupt myCAF-driven malignancy while preserving anti-tumor stromal functions." (PMID 40859405, 2025). "TCF12 expression was also evaluated across tumor stage (T1–T4) and histologic grade (G1–G3)." (PMID 40190273, 2025). "Future work will utilize orthotopic HCC mouse models to evaluate whether TCF12 knockdown synergizes with sorafenib to suppress tumor growth and angiogenesis." (PMID 40190273, 2025). "In our present study, the TCF12–MALAT1 alliance is significantly associated with a β-catenin-independent induction of cyclin D1 gene expression, which acts as a risk factor for CRC patient mortality, associated more with tumor recurrence than with metastasis." (PMID 39768127, 2024). "Gene expression analyses across these cell clusters confirmed that Ascl1/GFP, along with ASCL1 canonical NOTCH signaling target genes (Dll3, Notch1, Hes5) and the bHLH E-protein co-binding partners (Tcf4, Tcf12) were significantly elevated in Ascl1-OE tumor cells compared to control." (PMID 39609428, 2024). "In our study, we discovered that 8.3% of CRC patients, regardless of whether they experience tumor metastasis, have poor prognosis due to their tumor tissues expressing high TCF12 mRNA, high MALAT1, low β-catenin mRNA, and high cyclin D1 mRNA." (PMID 39768127, 2024). "GO terms suggest that TCF12 has DNA-binding and transcription factor activity; therefore, we speculate that TCF12 regulates tumor malignant progression by mediating gene transcription." (PMID 38725030, 2024). "In this study, we identified a subset (8.3%) of CRC patients who, irrespective of tumor metastasis, have a poorer prognosis due to their tumor tissues exhibiting high TCF12 mRNA, high MALAT1, low β-catenin mRNA, and high cyclin D1 mRNA levels, referred to as the TMBC pattern." (PMID 39768127, 2024). "Nevertheless, our data strongly suggest that TCF12 may play an additional role in maintaining multipotency of tumor stem cells and specifically inhibit differentiation towards oligodendrocytes." (PMID 37046694, 2023). "Our work demonstrates critical roles of TCF12 in GBM tumor progression." (PMID 37046694, 2023). "We observed the opposite effects when we injected TCF12 OE tumor cells into immunocompetent mice." (PMID 37046694, 2023). "This clearly demonstrates a role for TCF12 in the regulation of the cell cycle in GBM tumor cells." (PMID 37046694, 2023). "Finally, we observed that T-ALL onset was accelerated by 37 days in Cdkn1a-deficient mice, compared to the 53 day acceleration found in Heb/Tcf12+/- mice, confirming a tumor-suppressor function for Cdkn1a." (PMID 35401501, 2022). "Moreover, 16 of the top 20 CIS genes had supporting fusion transcripts from at least one tumor, including Cdkn2a, Nf1, Pten, Sox6, Sox5, Spred1, and Tcf12 (all containing PB splice acceptor fusions, implying transcript termination)." (PMID 32727536, 2020).